IL6 (interleukin 6)
Diseases named in the same sentence as IL6 in open-access papers (continued):
Sharing a sentence is not in itself a finding about the gene and the disease.
diabetic retinopathy (continued). "In this study, vitreous samples were obtained at the time of pars plana vitrectomy (PPV) in patients with diabetic retinopathy with and without PRP and whether vitreous levels of IL-6 and VEGF were influenced by PRP 2 weeks before PPV were investigated." (PMID 23675018, 2007). "While there are no studies recorded on the use of IL-6 inhibitors in treating CME from retinal vascular conditions, such as diabetic retinopathy or RVO, IL-6 inhibitors may provide another treatment option due the role of IL-6 in vascular inflammation and disruption of the blood–retina barrier." (PMID 36902105, 2023).
synovitis (73 papers, 2005 to 2025). Inflammation of a synovial membrane. "Recent integrative histopathological and clinical observations support the notion that rheumatoid synovitis has different patterns and that TNF-α and IL-6 are the primary causes of the two most common types of synovitis in RA, myeloid and lymphoid synovitis." (PMID 38715981, 2024). "The key finding of this study was that lower levels of pre-operative synovitis and higher levels of IL-6 and VEGFA were associated with better post-operative outcomes in UKA patients." (PMID 37449990, 2023). "Inflammatory cytokines (e.g. TNF-α, IL-17, IL-1β and IL-6) are known to be pathogenic factors triggering joint diseases and established synovitis." (PMID 34950033, 2021). "The presence of downstream proinflammatory biomarkers (s) IL6, was associated with osteophytes, synovitis, effusion, and meniscus extrusion, while that of (sf) IL6 was associated with effusion." (PMID 33282885, 2020). "In synovitis lesions, lymphocytes and synoviocytes produce large amounts of inflammatory cytokines, such as TNF, interleukin (IL)-1, and IL-6, which cause synovitis." (PMID 32944095, 2020). "In knee OA synovium with severe synovitis, increased IL-34 mRNA expression was directly associated with IL-6, IκB, NF-κB, and MMP-13, in addition to knee OA FLS." (PMID 32409720, 2020). "Previously, it was reported that SF IL-6 is associated with synovitis in the parapatellar subregion and knee pain." (PMID 31470613, 2019). "Our results provide evidence of LLLT-dependent reduction of IL-1β, IL-6 and TNFα, and the therapy's ability to inhibit proliferation of inflammatory cells makes it a suitable treatment for synovitis associated with the early stages of OA." (PMID 24028507, 2013). "Lower levels of synovitis and higher levels of IL-6 and VEGFA were associated with better post-operative outcomes after UKA, which could be helpful for identifying UKA patients in clinical practice." (PMID 37449990, 2023). "Synovitis was caused by persistent inflammatory responses, which were resulted from the increased number of inflammatory cells and the increased secretion of various inflammatory mediators, such as IL-1β, IL-6 and IL-17." (PMID 32256686, 2020). "Synovitis and loss of articular cartilage were also inhibited, and the articular cartilage area, as detected by safranin O positivity, was significantly smaller in hIL-1α cTg than control mice, a phenotype rescued by IL-6 deletion." (PMID 30361689, 2018). "Therefore, the levels of IL-6 represent an indicator of the inflammatory conditions caused by OA and secondary synovitis, and were found to be significantly decreased after IA HA treatments in the present study." (PMID 26914761, 2014). "In an OA mouse model, inhibition of IL-6 through IL-17RA-mediated pathways was found to suppress synovitis." (PMID 40589764, 2025). "During the clinical phase, TNF-α, IL-6, and IL-1β drive synovitis by activating macrophages and fibroblast-like synoviocytes, while also promoting RANKL (Receptor Activator of Nuclear factor κB Ligand) expression and osteoclast differentiation." (PMID 41010616, 2025). "Treatment with IL-6 inhibitors can positively affect these symptoms and exert substantial anti-inflammatory effects on synovitis." (PMID 38956271, 2024). "The results indicate that both IL-1β and IL-6 play pivotal roles in synovitis pathogenesis, with distinct expression levels across various subtypes." (PMID 38734632, 2024). "We discovered that DPA, a main component of omega-3 fatty acids, had a potential therapeutic effect on synovitis by significantly inhibiting the transcription and expression of IL-1β and IL-6 in RAW264.7 macrophages." (PMID 38734632, 2024). "Synovitis is responsible for the production of proinflammatory cytokines such as interleukin-6 (IL-6), tumor necrosis factor-α (TNF-α), and interleukin-1β (IL-1β)." (PMID 37021049, 2023).
synovitis (continued). "Directly after KJD synovitis seemed to be improved based on reduced villi formation and reduced SF IL-6 levels compared to OA controls." (PMID 36313973, 2023). "A positive correlation between levels of serum CRP and histologic evidence of synovitis and synovial fluid interleukin-6 (IL-6) at the time of joint replacement has also been demonstrated." (PMID 37656392, 2023). "Synovitis is caused by the synthesis of significant quantities of pro-inflammatory factors such as tumour necrosis factor (TNF), interleukin (IL)-1, and IL-6 by lymphocytes and synovial cells in synovitis lesions." (PMID 37206012, 2023). "Spearman's rank correlation coefficient (Rs) = 0.399 (P=0.016) between serum IL-6 levels and the synovitis grading suggests a direct correlation between IL-6 production and disease severity." (PMID 35692576, 2022). "The Spearman correlation coefficient (Rs) = 0.399 (P=0.016) between serum IL-6 levels and the synovitis grading suggested a direct correlation between IL-6 production and disease severity." (PMID 35692576, 2022). "Serum IL-6 levels were evaluated in parallel with disease severity expressed as synovitis grading of the affected joints." (PMID 35692576, 2022). "In RA sera, VEGF and IL-6 levels were elevated in proportion to synovitis severity, correlating with conventional markers for disease activity, including ESR, CRP, and DAS28." (PMID 32461558, 2020). "The presence of increased plasma IL-6 levels in conjunction with increased paw thickness and synovitis supports the contribution of a systemic and local inflammatory response." (PMID 32634159, 2020). "We demonstrated that D-lactate increased the expression and release of IL-6 in a dose-dependent manner, suggesting that the presence of this metabolite in the joint contributes to the onset of synovitis in cattle." (PMID 30932023, 2019). "Correlations were weak to moderate between changes in the RAMRIS synovitis score and changes in bDMARD-treated explants’ production of IL-6 or MCP-1." (PMID 29787569, 2018). "In patients with grade 3 cases of synovitis, the levels of TNFα, IL1β, IL6, and MMP1 were significantly increased compared with those in cases of grade 2 synovitis (p < 0.05)." (PMID 28425031, 2017). "Whereas IL-6, MCP-1 and MIP-1β were associated with synovitis detected by MRI or CFmax in combination, only MCP-1 and IL-6 were associated with the extent of BME and bone erosions visualised by MRI." (PMID 24886513, 2014). "For example, MCP-1 and IL-6 were associated with both general inflammation and bone destruction, in contrast to MIP-1β, which was involved solely in general synovitis." (PMID 24886513, 2014). "IL-6 plays an important role in pathogenesis of septic arthritis promoting synovitis, manifested by stimulation of chemokines and adhesion molecules and infiltration of inflammatory cells, such as macrophages and lymphocytes." (PMID 23431241, 2013). "The results of the present study are comparable with those of previous studies, which using a zymosan-induced mouse OA model, reported that TNFα is related to synovitis and that IL-6 has a role in reducing cartilage destruction." (PMID 21714933, 2011). "The results suggest that these cytokines play a role in the pathogenesis of synovitis in osteoarthritic knees in different ways: TNFα is correlated with pain, whereas IL-6 is correlated with joint function." (PMID 21714933, 2011). "At the affected joints, IL-6 has a pivotal role in the inflammatory process, in osteoclast-mediated bone resorption, and in synovitis." (PMID 22046525, 2011). "Additionally, our results indicated that the expression of IL-1β and IL-6 varied among different synovial tissue sections within the same type of synovitis, and its expression in the anterior medial region was significantly higher." (PMID 38734632, 2024). "Moreover, our results suggest that IL-1β and IL-6 are pivotal inflammatory factors in meniscal tears-induced synovitis." (PMID 38734632, 2024).
synovitis (continued). "Additionally, systemic blockading of IL-6 using an anti-IL-6 receptor-neutralizing antibody has been found to reduce cartilage lesions, osteophyte formation, and the severity of synovitis in mice with DMM-induced OA." (PMID 39771038, 2024). "Additionally, we identified the essential omega-3 fatty acid DPA as a potential therapeutic agent for synovitis, demonstrating efficacy in blocking the transcription and expression of IL-1β and IL-6 with minimal side effects." (PMID 38734632, 2024). "Interestingly, HtrA2 levels in the SF of RA patients were elevated in proportion to synovitis severity and correlated with the expression of proinflammation cytokines and chemokines, such as IL-6, IL-8, and CCL2." (PMID 37287073, 2023). "Besides, a significant correlation was found between serum IL-6 levels and the synovitis grading, suggesting a direct correlation between IL-6 production and disease severity." (PMID 35692576, 2022). "Taken together with the in vitro results, it was speculated that PTX alleviated synovitis might be related to the inhibition of cell migration and the expression of IL-1β, IL-6, and IL-8." (PMID 34566640, 2021). "In RA, TNF-α and IL-6 are the two well-known cytokines triggering synovitis and bone erosions." (PMID 33343563, 2020). "To this end, we measured the concentrations of VEGF, PlGF, soluble Flt-1 (sFlt-1), and IL-6 in the SF and/or sera of RA patients and compared them with synovitis severity defined by ultrasonography (US) and therapeutic responses to conventional DMARD (c-DMARD) versus b-DMARD." (PMID 32461558, 2020). "Consequently, in the SF of RA patients, PlGF and IL-6 levels correlated well with synovitis severity determined by US." (PMID 32461558, 2020). "Consequently, the predominant involvement of peripheral articular tissue in pSpA may result in high IL-6 secretion, thus reflecting synovitis." (PMID 36792786, 2023). "The synovitis induced by DMM could be alleviated by systemic blockade of IL-6." (PMID 32596310, 2020). "Synovitis and pannus formation were significantly reduced in the anti-IL-6 mAb treated mice as compared to that of the control mAb treated mice in the current study, indicating the efficacy of the anti-IL-6 mAb in suppressing histological degradation in this RA model." (PMID 19368720, 2009). "Inflammatory markers such as IL‐1β, IL‐6, TNF‐α and MMP1 increased with synovitis or severe chondral damage." (PMID 40989937, 2025). "TNF and IL-6 inhibitors, such as infliximab and tocilizumab, suppress VEGF production and are positively correlated with reductions in synovitis severity, as assessed by ultrasound." (PMID 41010616, 2025). "IL-6 and IFN-α/β are involved in the initiation of synovitis, specifically in synovial inflammation." (PMID 38675400, 2024). "Proinflammatory cytokines, such as IL-6, IL-1β, and TNF-α, contribute to the destruction of cartilage and synovitis." (PMID 38913985, 2024). "TP-VP NPs effectively down-regulated IL-1β, IL-6 and TNF-α levels to inhibit the erosion of synovitis and bone tissue, and alleviate the swelling and deformation of CIA mice’s feet." (PMID 35999774, 2022). "Our results show significant correlation between synovial IL-6, JAK2, STAT1; blood IL-6 and lympho-myeloid synovitis." (PMID 36465908, 2022). "Once OA synovitis starts, IL-1, TNF-α and IL-6 are over-produced and secreted to synovial fluid through activation of TLR4 by synovial cells." (PMID 36241903, 2022). "Expression levels of IL1B, IL6, CXCL8, TNF, PTGS2, and PTGER4 showed significant positive correlation with synovitis score." (PMID 33507995, 2021). "Expression levels of IL1B, IL6, CXCL8, TNF, PTGS2, and PTGER4 showed significant positive correlations with synovitis score." (PMID 33507995, 2021). "Severe synovial membrane inflammation (synovitis), where there is a 3–100-fold elevation of pro-inflammatory cytokines, such as TNF-α, interleukin-6 (IL-6), interleukin-1β (IL-1β), and CRP, leads to chronic synovitis." (PMID 33499333, 2021).
synovitis (continued). "Synovial IL-6 is also correlated with serum CRP, suggesting that serum CRP reflects synovitis in humans with OA, although these parameters were only weakly correlated in this report." (PMID 27575050, 2016). "Additionally, several cytokines such as IL-6 and TNF-alpha cytokines have the potential promote synovitis, resulting in further joint inflammation and cartilage degradation." (PMID 39274226, 2024). "Synovitis has been related to the production of TNF-α, IL-17, IL-6, and IL-1." (PMID 37446881, 2023). "In stratified analyses, relative IL-6 mRNA expression was significantly up-regulated in the synovium of knee OA patients with high-grade synovitis, as compared to those without synovitis (P < 0.05), consistent with NF-κB mRNA expression analysis (P < 0.05)." (PMID 35705674, 2022). "Regarding cytokine production in normal synovium, although very small amounts of pro-inflammatory cytokines, such as interleukin-1β (IL1β), interleukin 6 (IL-6), and tumor necrosis factor-alpha (TNF) are generated, levels are much lower than those present in any type of synovitis." (PMID 33968950, 2021). "Indeed, in vitro and in vivo studies have shown the major role played by IL-6, IL-8, NO and PGE2 in cartilage degradation and synovitis onset and progression." (PMID 26020773, 2015). "IPFP area was neither associated with BMI, body fat, trunk fat, leg muscle strength and patellofemoral synovitis, nor with leptin, IL-6 and TNF-α (data not shown)." (PMID 25008048, 2014). "Some, such as IL-6, were present in all inflammatory arthritides, suggesting their importance in synovitis per se rather than a specific role in rheumatoid synovitis." (PMID 15987480, 2005). "In addition, IL-8 and IL-6 have been described as NET inducers and therefore, we did not discard that the release of these cytokines induced by D-lactate contributes to NET release observed during synovitis in cattle with ARA." (PMID 33202791, 2020). "In addition, MKK3, but not MKK6, is required for optimal p38 activation in synovitis, whereas MKK6-deficiency is associated with lower IL-6, IL-17 and anti-collagen antibody production." (PMID 24855454, 2014). "Taken together, the effective inhibition ability of IL-1β and IL-6, and the absence of obvious side effects further support DPA as a promising agent for synovitis treatment." (PMID 38734632, 2024). "When we divided patients into two groups depending on the presence of active synovitis (GSUS ≥ 2 or PDUS ≥ 1), the levels of PlGF and IL-6, but not VEGF or sFlt-1, were significantly higher in patients with active synovitis than in those with inactive synovitis." (PMID 32461558, 2020).
allergic asthma (72 papers, 2009 to 2026). A asthma with a basis in a pathological type I hypersensitivity reaction. "Exacerbations of ovalbumin‐induced experimental allergic asthma were elicited in wild‐type and IL‐6‐deficient mice by intranasal (i.n.)application of poly(I:C)." (PMID 41099307, 2026). "These behavioral and neuroimmune changes in offspring occur in response to allergic asthma-associated elevations in inflammatory cytokines in the dams—namely, IL-4, IL-5, IL-6, and IL-17 —and closely mirror observations reported in clinical settings." (PMID 36009104, 2022). "IL-6 signaling was implied by an animal, genetic association, and clinical studies in allergic asthma." (PMID 35052792, 2022). "The evidence suggests that the IL-6/IL-17A axis is associated with fungal allergic asthma in conditions with B cell deficiency." (PMID 35740474, 2022). "For example, in a JH−/− (B cell-deficient) murine model of fungal allergic asthma, levels of the inflammatory cytokines IL-6 and IL-17A were significantly elevated, and there was significantly more robust airway eosinophilia and neutrophilia." (PMID 35740474, 2022). "Interleukin (IL)‐6 signalling has been implicated in allergic asthma by animal, genetic association and clinical studies." (PMID 31223480, 2019). "The association between the symptoms of allergic asthma and increased expression of IL-6 in patients was documented a long time ago." (PMID 30534125, 2018). "IL-6 was reported to promote IL-4 production during Th2 cell differentiation and inhibit Th1 differentiation, which caused IL-6 to be highlighted as a major potential contributor of the allergic asthma pathology." (PMID 37998734, 2023). "Thus, the Il-6/PI3K/Akt/NF-κB pathway causes enhanced inflammatory expression in Der p-induced allergic asthma." (PMID 31581442, 2019). "In summary, these results suggested that IL-6 from subtypes of myeloid cells, such as dendritic cells and macrophages, may play a pathogenic role in the development of allergic asthma." (PMID 30534125, 2018). "The levels of IL-6 were lower in sarcoidosis patients compared to HP (p = 0.02) and non-allergic asthma (p = 0.02) patients." (PMID 40725075, 2025). "IL-6 is the proinflammatory cytokine that influences allergic asthma and modulates the immune response by affecting the balance between regulatory T cells and Th17 cells." (PMID 39598467, 2024). "Screening results for phytocompounds of Z. rosea bulbs by GC-MS analysis were represented, which played a decisive role in the development of allergic asthma by affecting IL6, AKT1 and, Src genes." (PMID 39598467, 2024). "Here, we showed that our model of MAA recapitulates the exposure to cytokines that are hallmarks of the allergic asthma response, including increased levels of IL-4, IL-6, IL-5, IL-13, and IL-17." (PMID 36009104, 2022). "In severe neutrophilic asthma, IFN-γ and TNF-α are increased, while IL-6 is increased in non-allergic asthma compared to allergic asthma." (PMID 35887796, 2022). "Increased levels of IL-6 were detected in the sputum of asthmatic subjects when compared to healthy controls, which correlated with impaired lung function in allergic asthma." (PMID 35885021, 2022). "For the sake of exploring the regulation of inflammatory factors of FDCM in OVA-sensitized allergic asthma, the expression of IL-1β and IL-6 was detected by Western blotting." (PMID 35431951, 2022). "Recent evidence has suggested that the level of IL-6 in peripheral blood of patients with allergic asthma was increased significantly during the onset of the disease." (PMID 34402724, 2021). "Compared to healthy children of the same age, the allergic asthma patients exhibited significantly increased IL-17 and IL-6 expression levels and a marked decline in TGF-β and IL-10 expression levels." (PMID 32834826, 2020).